FOXP3 (forkhead box P3)
Diseases named in the same sentence as FOXP3 in open-access papers (continued):
Sharing a sentence is not in itself a finding about the gene and the disease.
breast carcinoma (continued). "Elevated FoxP3 expression and Treg cell expansion are generally considered to poor prognosis markers in various cancers, including breast cancer, gastric malignancies, lymphoma and so on." (PMID 30479566, 2018). "Immunohistochemical staining was then performed to detect the expression of FOXP3 and vessel density in 93 human breast cancer tissue specimens." (PMID 29970908, 2018). "To assess the possibility of interaction between FOXP3 and Gal-1 in vivo, we examined the expression of Gal-1 in 53 pairs of nuclear FOXP3-positive breast cancer tissue and adjacent normal tissue samples." (PMID 29549328, 2018). "Overexpression of Foxp3 in two breast cancer cell lines downregulated both mRNA and protein expression levels of CD44." (PMID 29747682, 2018). "Taken together, our data demonstrate that FOXP3 suppresses breast cancer angiogenesis by downregulating VEGF expression." (PMID 29970908, 2018). "Taken together, our data suggest that FOXP3 plays an important role in VEGF-mediated angiogenesis in breast cancer." (PMID 29970908, 2018). "A small number of studies, including our own, have found that high levels of CD8+ T cells in primary breast cancers were associated with a pCR following NAC; a high CD8+: FOXP3+ T cell ratio was also significantly associated with a pCR." (PMID 29390966, 2018). "The subsequent cellular functional experiments indicated that, the inhibitory effects of FOXP3 on the proliferation and metastasis of breast cancer cells in vitro were indeed abolished by the interaction of FOXP3 and Gal-1." (PMID 29549328, 2018). "Taken together, CCL1 expressing immune cells and FoxP3+ Treg are significantly increased in invasive breast cancer tissues compared to healthy breasts." (PMID 30572845, 2018). "Although FOXP3 is well known to be expressed in regulatory T cells and associated with their differentiation and function, recent studies have explored the hypothesis that FOXP3 is expressed not only in normal breast epithelium and also in breast carcinoma cells." (PMID 29534468, 2018). "In summary, our in vitro and in vivo analyses provide preliminary evidence that FOXP3 is indeed a suppressor of angiogenesis in breast cancer." (PMID 29970908, 2018). "We conclude that down regulation of ZEB2 by miR-155 and FOXP3 alters the migratory and invasive potential of breast cancer cells." (PMID 29963231, 2018). "Herein, we show for the first time that FOXP3 acts as a transcriptional activator of the human UBC9 gene in MCF7 breast cancer cells." (PMID 30011797, 2018). "Similar positive score for Foxp3 immunoexpression was observed in pancreatic cancer cells (61%), and breast cancer tissues (57% and 73%)." (PMID 28669079, 2018). "High FOXP3 expression was a protective factor for breast cancer survival (HR = 0.77, log-rank P < 0.001), while high VEGF expression was a deleterious factor for breast cancer survival (HR = 1.34, log-rank P < 0.001)." (PMID 29970908, 2018). "To verify that FOXP3 regulates the endogenous ZEB2 gene, we examined the effect of enforced FOXP3 expression in BT549 breast cancer cells, which normally have low levels of FOXP3 and express ZEB2." (PMID 29963231, 2018). "FOXP3 expression is likewise higher in HMECS compared with its expression in human breast cancer cell lines." (PMID 29963231, 2018). "Expression of ARHGAP15 is therefore considered to be regulated by several mechanisms other than androgens, such as FOXP3, in breast carcinomas." (PMID 29534468, 2018). "In the present study, clinical specimen analyses, in vivo animal model experiments, and in vitro cytological experiments indicated that FOXP3 is indeed a suppressor of breast cancer angiogenesis." (PMID 29970908, 2018). "High FoxP3+ Tregs was associated with worse OS in cervical, renal cell carcinoma (RCC), melanoma, HCC, gastric and breast cancers and an improved OS in CRC, head and neck cancer (HNC), and oesophageal cancer whereas the DFS rate was lower in lung cancer." (PMID 29872507, 2018).
breast carcinoma (continued). "Using co-IP and FRET analysis, we found that the interaction of FOXP3 with Gal-1 occurred mainly in the nucleus of breast cancer cells." (PMID 29549328, 2018). "For instance, overexpression of FOXP3 is associated with worse prognosis in NSCLC, colorectal cancer, and cervical cancer but good prognosis in breast cancer, prostate cancer, and gastric cancer." (PMID 30360388, 2018). "To investigate the relationship between FOXP3 and VEGF expression, we measured the expression levels of FOXP3 and VEGF in the same 93 human breast cancer samples that were used in the FOXP3 study." (PMID 29970908, 2018). "Three thousand highly metastatic, murine, syngeneic mammary carcinoma 4T1 cells were injected orthotopically into FoxP3-GFP Balb/c mice to establish a single primary tumor per mouse (N=11 for each group)." (PMID 30034628, 2018). "Oesophageal adenocarcinoma patients with a high CD8+ T cells density after NACT had a favorable clinical outcome, while the presence of Foxp3+ TILs in breast cancer patients predicted a good response to NACT and a favorable prognosis." (PMID 30474571, 2018). "By analyzing 93 clinical breast cancer samples, we found that tumor angiogenic activity is negatively correlated with FOXP3 expression." (PMID 29970908, 2018). "We also demonstrate that FOXP3 can inhibit breast cancer angiogenesis via the transcriptional suppression of VEGF." (PMID 29970908, 2018). "Here we show by overexpression of FOXP3 and/ or miR-155 that in aggressive breast cancer lines ZEB2 is regulated independently of ZEB1, both transcriptionally, by FOXP3 and post-transcriptionally by miR-155." (PMID 29963231, 2018). "Given the importance of FOXP3 as a breast cancer suppressor, it is surprising that a substantial number of breast cancer samples are FOXP3-positive." (PMID 29549328, 2018). "Altogether, nuclear Gal-1 interferes with the binding of FOXP3 to DNA by interacting with the FKH domain of FOXP3, and it indicates a possible mechanism for the loss of the tumor-suppressive properties of FOXP3 in wild-type FOXP3-positive breast cancer." (PMID 29549328, 2018). "It is well established that high infiltration by FoxP3+ Treg has an adverse effect on prognosis in breast cancer." (PMID 30572845, 2018). "Here we found that the clinical expression of nuclear FOXP3 was inversely correlated with breast cancer angiogenesis." (PMID 29970908, 2018). "Our results indicate a novel function for nuclear Gal-1, in mediating the loss of the tumor-suppressive function of FOXP3 through interaction with the FKH domain and inhibition of the DNA-binding ability of FOXP3 in breast cancer cells." (PMID 29549328, 2018). "To examine if this finding in our mouse model represented an important disjunction from human breast cancer, we once again interrogated breast cancer outcomes based upon FOXP3 gene expression in the TCGA data set." (PMID 30285905, 2018). "The strong correlation between TGFβ pathway activation and FOXP3 expression was also noted in a TCGA breast cancer data set (n = 776), using normal breast tissue as a reference." (PMID 29467463, 2018). "How the blockade of Gal-1-FOXP3 interaction affects tumor progression in wild-type FOXP3-positive breast cancer animal models needs further study." (PMID 29549328, 2018). "Transient knock-down of Foxp3 from breast cancer cell lines upregulated both mRNA and protein level of CD44, indicating that Foxp3 is a negative regulator of CD44." (PMID 29747682, 2018). "Notch1, which is a key regulator of luminal estrogen receptor (ER+) breast cancers is inversely correlated with the aggressive TNBC/basal-like breast carcinomas and infiltrating Foxp3+ Tregs." (PMID 30061899, 2018). "Strikingly, we found significantly increased numbers of CCL1 and FoxP3 expressing cells in breast cancer tissues compared to normal breast tissues." (PMID 30572845, 2018).
breast carcinoma (continued). "On one hand, FOXP3 can inhibit breast cancer cell proliferation by regulating the expression of breast cancer oncogenes such as HER2, MYC and SKP216, 19–22." (PMID 29970908, 2018). "First we were able to observe that involution associated murine mammary tumors possess fewer intratumoral T cells overall, with a specific decrease within the CD4+ T cell compartment of Foxp3+ T cells." (PMID 30285905, 2018). "The cytoplasmic localization of FOXP3 was detected in several human cancers, including human breast carcinoma." (PMID 28903735, 2017). "In other studies on colorectal, gastric and breast cancer there has also been a positive correlation between high expression of FOXP3 and favorable clinical outcome." (PMID 28851300, 2017). "FOXP3 has been reported as a suppressor gene in breast cancer and prostate cancer via repressing the expression of oncogene such as HER2, SKP2, p21, LATS2 and c-Myc." (PMID 28716029, 2017). "As pDCs are the principal producers of IFN-α to initiate innate immune responses, suboptimal IFN-α production promotes the expansion of FOXP3(+) regulatory T cells, leading to poor prognosis in breast cancer patients." (PMID 27374101, 2017). "In contrast with these data, FOXP3 was demonstrated to be a transcriptional repressor of two breast cancer oncogenes, SKP2 and HER2, acting as a potential tumor suppressor gene." (PMID 28903735, 2017). "Nevertheless, to the best of our knowledge, high infiltration of FoxP3+ Tregs was a strong factor for unfavorable outcome in various solid tumors, such as breast cancer, non-small cell lung cancer and hepatocellular carcinoma." (PMID 29209232, 2017). "Studies also reported that many tumor cell lines including lung cancer, colon cancer, breast cancer, melanoma, acute T-cell leukemia cell lines can express FOXP3 protein." (PMID 28029650, 2017). "By use of laser-capture microdissection, Foxp3+/+ or Foxp3sf/+ breast epithelial cells and Foxp3sf/+ breast cancer cells were obtained from these mice, and the levels of miR-200 s in the microdissected cells were measured." (PMID 28637482, 2017). "Our results have suggested that FOXP3 can function as an oncogene in NSCLC that has a different genetic background from breast cancer and prostate cancers." (PMID 28716029, 2017). "Tumor FOXP3 has been claimed as an independent prognostic indicator for tongue squamous cell carcinoma and breast cancer." (PMID 28716029, 2017). "In fact, we show here that up-regulation of the mRNA expression levels of PD-L1, FOXP3, CD80, CD40, and CD14 in PBMCs is associated with breast cancer." (PMID 26942414, 2017). "In conclusion, our data showed that the mRNA expression levels of PD-L1, FOXP3, CD80, CD40, and CD14 in PBMCs were associated with breast cancer burden." (PMID 26942414, 2017). "IDO has the ability to showimmunosuppressive effects by increasing theinfiltration of Foxp3+ regulatory T cells in patientswith breast cancer." (PMID 28367424, 2017). "In the present work, we explored the relevance of FOXP3-mediated transcriptional regulation of miR-200 s in breast cancer cells in mice and humans." (PMID 28637482, 2017). "There was a positive correlation between expression of FOXP3 and miR-155 in breast cancer cell lines and primary breast cancers." (PMID 28562349, 2017). "Conversely, in breast cancer MSCs conferred immune protection through TGF-β1-mediated generation of forkhead box P3 (FoxP3)+ Tregs (regulatory t cells), that in turn suppressed tumor cell cytolysis by CD8+ T cells and natural killer (NK) cells." (PMID 29069870, 2017). "In our studies on breast cancer patients, we have demonstrated that FoxP3+ Treg frequency is 2–3 times higher in breast cancer patients (19% vs. 7%) over normal subjects." (PMID 28304339, 2017).
breast carcinoma (continued). "FOXP3 functions as a tumor suppressor in breast cancer cells but also induces expression of oncogenic miR-155 through inhibition of BRCA1, representing a heterogeneous network of the target genes affected in FOXP3-mediated tumor suppression." (PMID 28562349, 2017). "Other finds were including but not only that 80% of the normal epithelial cells in breast tissue expressed FOXP3 and only 20% of breast cancer tissue expressed it by IHC." (PMID 28029650, 2017). "In in vitro and in vivo studies, FOXP3 has been widely reported as a suppressor gene in breast cancer and prostate cancer." (PMID 28716029, 2017). "In contrast to BRCA1 and p63, which are transcriptional repressors of miR-155, FOXP3, a member of the forkhead-box/winged-helix transcription factor family, is a transcriptional inducer of miR-155 in the breast cancer cell lines, BT549 and MDA-MB-231." (PMID 28562349, 2017). "As a suppressor gene in breast cancer cells, there was also research showing that interaction of Runx1 and FOXP3 genes can affected gene expression profile of mammary epithelial cell gene and finally Runx1 cause breast cancer progression on FOXP3 availability." (PMID 28029650, 2017). "We investigated FOXP3-inducible breast cancer cells, Foxp3 heterozygous Scurfy mutant (Foxp3sf/+) female mice, and patients with breast cancer for characterization of the formation and regulation of the miR-200 family in breast cancer cells and circulation." (PMID 28637482, 2017). "Increases in FOXP3+Treg infiltration and PD-L1 expression have been revealed in gastric cancer tissues, colorectal carcinoma, and breast cancer." (PMID 28837143, 2017). "In our study, the majority of breast samples were HER2 −ve and in only one specimen was FOXP3+expressed in the breast cancer cells." (PMID 27777963, 2016). "For instance, a FGFR1-related gene set showed an interaction relationship with FOXP3 under ER modulation, yet another unexplored interaction in breast cancer discovered by our study of interaction under modulation." (PMID 26972162, 2016). "The relationship between FOXP3+ TILs and several clinicopathological features of breast cancer was also evaluated." (PMID 27566250, 2016). "It has been proposed that FOXP3 participates in breast cancer development as a tumor suppressor factor directly bound to its oncogene and miR-146a promoter targets." (PMID 26735887, 2016). "There was a significant reduction of FOXP3+ T cells in the blood (% [p = 0.001], absolute numbers (AbNs) [p = 0.001]) and breast cancers (intratumoural [p = 0.001], stromal [p = 0.001]) following 8 cycles of NAC in the same cohort of 16 patients." (PMID 27777963, 2016). "Interest has focused on the possible contribution of FOXP3+TILs to prognosis and pathological responses in breast cancer induced by NAC and is a matter of continuing debate." (PMID 27777963, 2016). "Hormone receptor positive HER2 negative tumors tend to have the least immune infiltrate yet are the only breast cancer subtype to show worse prognosis with increased FOXP3 regulatory T-cell infiltrate." (PMID 27777769, 2016). "In breast cancer, the FOXP3 has been described as a transcriptional repressor of genes involved in tumor development, like HER2 and SKP2, and also in cancer progression, like CXCR4." (PMID 27830498, 2016). "In HER2 overexpressing breast cancers, a high CD8+ : FOXP3+ T cell ratio was associated with a pCR and an improved DFS and OS." (PMID 27777963, 2016). "It has been shown that prognostic value of FOXP3 in breast cancer depends on localization of this protein as well as HER2 and ER expression." (PMID 26735887, 2016). "We pooled overall survival (OS) and relapse free survival (RFS) to assess the impact of FOXP3+ TILs level on the prognosis of breast cancers." (PMID 27566250, 2016).
breast carcinoma (continued). "The present results of meta-analysis showed that higher FOXP3+ TILs level in patients with breast cancer led to poor overall survival (OS) and was significantly associated with c-erbB-2 status, lymph node status, ER status and PR status." (PMID 27566250, 2016). "The pooled results showed that a higher density of FOXP3+ lymphocytes in tumor tissue was a promising prognostic factor for OS of breast cancers." (PMID 27566250, 2016). "On the other hand, ER positive or PR positive breast cancers were accompanied with lower FOXP3+ TILs level." (PMID 27566250, 2016). "In an oncogenic context, physical interaction of FOXP3 with the transcription factor RUNX1 has been shown to regulate the expression of breast cancer related genes." (PMID 27588474, 2016). "In short, studies to confirm the clinical significance of FOXP3+ TILs in breast cancer are still insufficient and the prognostic value still lacks assessment, especially in different molecule types of breast cancer." (PMID 27566250, 2016). "The correlation between FOXP3+ tumor-infiltrating lymphocytes(TILs) and breast cancer prognosis was analyzed." (PMID 27566250, 2016). "In a cohort of patients with HER2 +ve cancers there was a better OS and DFS if the breast cancer cells themselves expressed FOXP3+, possibly acting as a tumour suppressor gene." (PMID 27777963, 2016). "But PD-1+ and Foxp3+ subtype TILs highly expressed in hormone receptor (−), HER-2(+) breast cancer, which have a high risk of recurrence and metastasis." (PMID 26459255, 2016). "Breast cancers with higher FOXP3+ TIL level were positively correlated with c-erbB-2 status(pooled RR:1.52, 95 % CI:1.32–1.75; P < 0.05), lymph node status(pooled RR:1.17, 95 % CI:1.04–1.32; P < 0.05)." (PMID 27566250, 2016). "In breast cancers, the percentage of Tregs, as assessed by Foxp3 positivity, increases in parallel with the disease stage, indicating that the presence of Tregs promotes tumor progression through immunosuppression." (PMID 27246354, 2016). "A higher CD8+/FOXP3+ TILs ratio has been related to favorable prognosis in aggressive breast cancer, ovarian cancer and osteosarcoma." (PMID 27683115, 2016). "High levels of FOXP3+T cells have been found to be significantly increased in HER2 +ve breast cancers." (PMID 27777963, 2016). "In our study, FOXP3+T cells were also prominent in HER2 −ve cancers (major phenotype in breast cancer)." (PMID 27777963, 2016). "One study demonstrated that Foxp3 inhibited breast cancer cell adhesion, invasion and metastasis, while study on the molecular mechanism revealed that Foxp3 inhibited breast cancer metastasis by down-regulating CD44 expression directly." (PMID 27457382, 2016). "Paradoxically, high levels of FOXP3+Tregs in ER −ve breast cancers (less common type of breast cancer) were shown to be associated with a good clinical outcome." (PMID 27777963, 2016). "The prognostic significance of FOXP3+ tumor-infiltrating lymphocytes (TILs) in patients with breast cancer remains controversial." (PMID 26475790, 2015). "In breast cancer cells, chromatin immunoprecipitation sequencing was used to identify a series of potential FOXP3-targeted miRs." (PMID 26682271, 2015). "This meta-analysis provided evidence to estimate the significance of FOXP3+ TILs detection in patients with breast cancer by summarizing all related studies." (PMID 26475790, 2015). "In conclusion, the results of this meta-analysis indicate that the prognostic role of FOXP3 expression in operable breast cancer cases depends on the FOXP3-positive region, the ER status, the geographic region and the FOXP3-positive cut-off value." (PMID 26305693, 2015). "In a stratified analysis for breast cancer, the prognostic significance of FoxP3+ Tregs varied based on the estrogen receptor (ER) status." (PMID 26462617, 2015).